IL1B (interleukin 1 beta)
Diseases named in the same sentence as IL1B in open-access papers (continued):
Sharing a sentence is not in itself a finding about the gene and the disease.
Insulin resistance (continued). "In this study, thiamine decreased the levels of FBG and sera insulin along with reduction of insulin resistance by elevation of insulin function and sensitivity following the decrement of levels of IL-1β, FFA, glycation products, oxidative stress markers, and hepatic expression of NF-kβ." (PMID 33995940, 2021). "In this study, we observed that PU supplementation remarkably decreased gut microbiota disturbance-induced release of TNF-α and IL-1β, thus inhibiting the IKKβ/NF-κB inflammatory pathway phosphorylation and reducing the production of TNF-α and IL-1β, thereby improving insulin resistance." (PMID 34262422, 2021). "Also, interleukin 1 beta (IL1B), a pro-inflammatory pleiotropic cytokine, plays an important role in insulin resistance." (PMID 33952720, 2021). "Interestingly, whereas saturated fatty acid activates the NLRP3 inflammasome in mice and contributes to insulin resistance, unsaturated fatty acid attenuates IL-1β-mediated insulin resistance by preserving AMPK activity." (PMID 33546399, 2021). "In addition, IL-1β plays a role in T2D, by its involvement in the pathogenesis of insulin resistance and ultimately promoting islet cell death." (PMID 33904577, 2021). "The neutralization of pro-inflammatory cytokines, especially IL-1β, may extinguish the inflammatory process of the pancreatic islets and thus normalize blood glucose levels and reduce insulin resistance." (PMID 33546399, 2021). "While primarily considered a pro-inflammatory marker, IL-1β also influences insulin secretion and insulin resistance in mice, and could therefore play a primarily metabolic role in fasting-adapted NES, which display insulin resistance." (PMID 34744798, 2021). "Moreover, IL-1β contributes to the expression of tumor necrosis factor alpha (TNFα), which also promotes insulin resistance." (PMID 33546399, 2021). "Together, our findings suggest that skeletal muscle could contribute to plasma IL-1β through increased NLRP3 expression in this tissue during insulin resistance." (PMID 34638553, 2021). "GAL-3BP is significantly positively associated with inflammatory markers, including IL6, IL-1β, together with TNFα, and these may participate in MetS pathogenesis related to GAL-3BP, since inflammation may probably result in insulin resistance." (PMID 34858323, 2021). "In the adipose tissue of such individuals, the expression of the NLRP3 inflammasome components, the activity of caspase-1, and the level of IL-1β are increased, all of which are directly correlated with insulin resistance, metabolic syndrome, and the severity of T2DM." (PMID 33546399, 2021). "Hyperglycemia in severely ill, non-diabetic patients is believed to be caused by the cytokines (interleukin (IL)-1β and tumor necrosis factor (TNF)-α) that induce insulin resistance, and by hepatic gluconeogenesis driven by glucagon, catecholamines, cortisol, and growth hormone." (PMID 34202952, 2021). "A previous observational study demonstrated that a combined elevation of IL-1β and IL-6 was associated with a roughly threefold increased risk of T2DM, and IL-1β might induce insulin resistance via activating the IκB kinaseβ." (PMID 34754627, 2021). "Growing evidence suggests that IL-1β up-regulation contributes to the recruitment of adipose tissue macrophages and induction of additional pro-inflammatory cytokines, contributing to impaired fat-liver crosstalk thereby resulting in insulin resistance." (PMID 33076522, 2020). "Moreover, IL-1β, which also signals through IKKβ and NFκB, favors insulin resistance by repressing IRS-1 expression at both transcriptional and post-transcriptional levels." (PMID 32140136, 2020). "The activated ATMs then secrete various proinflammatory cytokines, such as TNF-α and interleukin-1β (IL-1β), which could lead to systemic insulin resistance due to endocrine actions." (PMID 33208918, 2020).
Insulin resistance (continued). "In addition, we observed that both senolytics induced a non-significant but evident reduction in the mRNA expression of the SASP factors Il6, Tnf and Il1b, proposed as mediators of insulin resistance." (PMID 32584785, 2020). "Also, out of 28 patients with chronic olanzapine consumption (unspecified dose) 14 were insulin-resistant and had a higher concentration of TNF-α, IL-6, IL-1β, and IL-8 with a positive correlation between these values and insulin resistance." (PMID 32373066, 2020). "Moreover, the expression of TLR2, TNF-α and IL-1β in old mice is also increased, thereby inhibiting Akt and mTOR activity and promoting insulin resistance." (PMID 32082422, 2020). "Similarly, female Sprague-Dawley rats and female BALB/c mice, after 8 weeks of treatment (10 mg/kg/day), exhibited a significant increase in TNF-α, IL-6, IL-1β, and IL-8 levels, in addition to insulin resistance." (PMID 32373066, 2020). "Finally, we focus on the consequences of inflammatory responses, in particular, the effect of TNF-α, IL-1β and IL-6 on insulin resistance." (PMID 31363792, 2019). "In a report from 2014, Henriksbo and colleagues showed that long-term treatment of obese mice with fluvastatin promoted insulin resistance in adipose tissue and increased caspase-1 activity and IL-1β production in adipose tissue explants in the presence of LPS." (PMID 31652822, 2019). "Another important cytokine involved in PA-induced insulin resistance is IL-1β." (PMID 31363792, 2019). "Among the many consequences of IL-1β production is the development of insulin resistance." (PMID 31920905, 2019). "It is well-known that FFA activates the proinflammatory NF-κB pathway in skeletal muscle and increases the expression of several cytokines including TNF-α, IL-1β, and IL-6 in liver, resulting in insulin resistance including activation of c-Jun NH2-terminal kinase (JNK)." (PMID 31447776, 2019). "The binding of LPS with TLR4 could result in the stimulation of IKKβ and NF-κB and then increase the levels of downstream inflammatory factors (like TNF-α, IL-6, IL-1β, etc.), which promoted the insulin resistance in the tissue where they were produced." (PMID 30210342, 2018). "Levels of FL and pentosidine may be increased by decline in glucose tolerance related to insulin resistance driven by increased IL-1β, producing increased early-stage protein glycation and increased pentose-derived metabolite precursors of pentosidine." (PMID 29929535, 2018). "IL-1β also induced insulin resistance in keratinocytes through the p38 MAPK pathway." (PMID 30116147, 2018). "The increases in monocyte TLR4 and phosphorylated JNK and p38 levels caused by lipid infusion were associated with enhanced production of multiple cytokines, including IL-1β, IL-6, MCP-1, and TNFα, all of which have been implicated in insulin resistance and type 2 diabetes." (PMID 29649324, 2018). "IL-1β also induces epigenetic changes that promote insulin resistance." (PMID 30116482, 2018). "Studies suggest that inflammasome activation, through IL-1β activation, may contribute to insulin resistance and type II diabetes." (PMID 28182687, 2017). "Alternative M2 macrophages sustain insulin sensitivity via the secretion of anti-inflammatory cytokines such as IL-4 and IL-13, while classical M1 macrophages secrete pro-inflammatory cytokines such as TNF-α, IL-6, and IL-1β, which, in turn, leads to insulin resistance and NASH." (PMID 28420094, 2017). "Our observation of diminished IL-1β expression in the serum and spleen of GSTO1-1 deficient mice treated with LPS therefore reveals a possible mechanism by which GSTO1-1 deficiency attenuates insulin resistance in mice on a high fat diet." (PMID 29259211, 2017). "Increases in IL-1β, IL-6, and TNF-α are associated with insulin resistance and glucose intolerance." (PMID 28420148, 2017). "Indeed, IL-1β induces insulin resistance by decreasing IRS-1 protein and inhibiting insulin-induced PKB phosphorylation." (PMID 28765650, 2017).
Insulin resistance (continued). "Furthermore, M1 macrophages secrete pro-inflammatory cytokines including TNFα, IL-1β, and IL-6, some of which can directly alter insulin receptor signaling in adipocytes, leading to insulin resistance." (PMID 29163218, 2017). "In particular, hepatic macrophages, which include both resident Kupffer cells and recruited bone marrow-derived macrophages, are the major immune cells that secrete inflammatory mediators, such as tumor necrosis factor (TNF)-α and interleukin (IL)-1β, leading to systemic insulin resistance and NASH." (PMID 28420094, 2017). "Next, we studied whether the NLRP3 inflammasome-dependent IL-1β production contributed to insulin resistance." (PMID 29096724, 2017). "The IL-1β inhibit IRS-1 signaling to promote insulin resistance." (PMID 28166749, 2017). "Excess IL-1β impairs islet function by inducing insulin resistance and β-cell apoptosis." (PMID 27152706, 2016). "IL-1β-induced cone insulin resistance, decreased glucose uptake and subsequent cone starvation might explain the CS loss in RP and AMD." (PMID 27438413, 2016). "Interestingly enough, these cytokines have been implicated in insulin resistance (TNF-α, IL-6, and IL-1β), atherosclerotic plaque destabilization (IL-18), and future cardiovascular events (IL-6, IL-18, IL-1β, and TNF-α)." (PMID 27034691, 2016). "IL-1β controls inflammatory responses and is involved in the development of insulin resistance." (PMID 26940592, 2016). "The level of IL-1β gradually increases from the development of normal glucose tolerance to impaired glucose tolerance to type 2 diabetes and is positively correlated with insulin resistance." (PMID 26881256, 2016). "Insulin resistance might be caused by pro-inflammatory cytokines, and we found that IL-6, TNF-α and IL-1β were up regulated in aged male GADD34-deficient mice." (PMID 26316333, 2015). "One study has demonstrated that conditioned medium from 3T3-L1 adipocytes stimulated with TNFα induced insulin resistance in hepatocytes, and this could be prevented by blocking TNFα-induced IL-1β production by 3T3-L1 cells." (PMID 24918199, 2014). "As macrophage-derived factors enhance adipocyte lipolysis, which may induce insulin resistance in multiple organs, we also investigated whether IL-1β mediates macrophage-induced lipolysis in human adipocytes." (PMID 24918199, 2014). "The expressions of IL-1β and inflammasome components have been found to increase in obese individuals; some of these components are related to the development of metabolic disorders such as insulin resistance." (PMID 25324698, 2014). "It has been hypothesized that activated innate and adaptive immune cells stimulate release of cytokines such as TNFα and IL-1β, which promote both systemic insulin resistance and β-cell damage." (PMID 25102180, 2014). "Besides the direct effects of inflammatory cytokines on lipogenesis and fibrogenesis, MCP-1, TNF-α, and IL-1β, IL-6 can induce insulin resistance." (PMID 25136608, 2014). "In addition, IL-1β induces insulin resistance in the keratinocytes, which in turn alters their proliferation and differentiation." (PMID 23935446, 2013). "Reducing the activity of inflammasome and suppressing IL-1β secretion might be targets to attenuate insulin resistance in diabetes." (PMID 23964268, 2013). "Insulin resistance is associated with a state of chronic low-grade inflammation, and mediators such as tumor necrosis factor-α (TNF-α), interleukin 1beta (IL-1β), and interleukin-6 (IL-6) have been identified as being involved in metabolic control and impairment in insulin-receptor signaling." (PMID 22927832, 2012). "They interfere with adipocyte function through the production of pro-inflammatory cytokines such as TNF-α, IL-1β and IL-6, which can lead to insulin resistance, modify adipokine secretion and lead to an excess of free fatty acid secretion through increased lipolysis and diminished lipogenesis." (PMID 23201837, 2012).
Insulin resistance (continued). "Pro-inflammatory cytokines: TNF-α, IL-6 and IL-1β are synthesized by numerous tissues, including obese adipose tissue, which, in addition to their well described pro-inflammatory properties, are involved in the genesis of insulin resistance." (PMID 23201837, 2012). "In this respect, we cannot exclude that the stimulating effect of IL-1β on β-cell function could play a part in the high plasma insulin levels that compensate for insulin resistance in obese rats." (PMID 21826222, 2011). "Elevated levels of interleukin-1β (IL-1β) and interleukin-1 receptor antagonist (IL-1 Ra) have been detected in subjects with essential hypertension and they are known to contribute to the development of insulin resistance and MetS." (PMID 19707530, 2009). "Interestingly, those expressions of “contractil genes” are associated to an increase of pro-inflammatory cytokines (TNFα, IL6 or IL1b) in insulin-resistance condition, while the presence of minoxidil or nebivolol reduces significantly the expressions of IL6 and IL1b." (PMID 41049496, 2025). "Insulin resistance may contribute significantly to the development of MASLD and its induced abnormalities in lipid metabolism can lead to increased production of proinflammatory cytokines, such as TNF-α, IL-1b, and IL-6, as well as less adiponectin, thereby inducing systemic insulin resistance." (PMID 40567989, 2025). "In obesity, insulin resistance and T2D, PA-induced activation of monocyte/macrophages enhances the production of inflammatory cytokines like tumor necrosis factor-alpha (TNF-α) and Interleukin (IL)-1β, and dysregulates key macrophage functions implicated in inflammatory cardiometabolic diseases." (PMID 40068774, 2025). "In insulin resistance states, microglial cell function is disrupted, causing polarization toward the pro-inflammatory M1 phenotype and the release of inflammatory factors such as TNF-α (Tumor Necrosis Factor-alpha) and IL-1β (Interleukin-1 beta), which result in cellular damage." (PMID 40895109, 2025). "Compensatory hyperinsulinemia that ensues excessive dietary carbohydrate intake or early-stage insulin resistance in overweight or obese patients may provoke macrophages to release proinflammatory cytokines like IL-1β, which in turn may render insulin target cells insulin-resistant." (PMID 36177037, 2022). "Downregulation of CRP, TNF-α, and nitrites and upregulation of adiponectin could be responsible for LTBI mediated protection against insulin resistance (IR), while the high levels of IL-1β, IL-12, and leptin could be responsible for IR mediated anti-TB immunity." (PMID 35832818, 2022). "Thus, IL‐1β is capable of impairing insulin signalling and action in hepatocytes and thus could participate in the development of hepatic insulin resistance." (PMID 36101976, 2022). "Anti-inflammatory agents such as salicylates, TNF-α antagonists, IL-1β antagonists, leukotrienes, and CA may be useful in developing therapeutics for obesity-related diseases, including insulin resistance, type 2 diabetes, and atherosclerotic cardiovascular disease." (PMID 36015301, 2022). "Also, chronically elevated levels of inflammatory cytokines such as CRP, TNF-a, IL-6, and IL-1b could enhance insulin resistance (IR), disrupt insulin sensitivity, and consequently impair glucose homeostasis resulting in an increase in the risk of T2DM." (PMID 34917685, 2021). "IL-1β, a pro-inflammatory cytokine, could induce insulin resistance in psoriasis." (PMID 34512732, 2021). "However, in livers from 1YO offspring of WSD-fed mothers with insulin resistance, we found an increase in macrophage recruitment and markers of inflammation, including IL1B, CD68, and CD11B in whole-liver tissue, and isolated hepatic macrophages were hyperresponsive to LPS." (PMID 34935645, 2021). "Moreover, FOXO1 could promote the production of IL-1β in macrophages and contribute to insulin resistance." (PMID 34637688, 2021).
Insulin resistance (continued). "- ↓ plasma triglycerides, liver lipids, liver triglycerides, insulin resistance, fasting glucose, fasting insulin, thoracic circumference, abdominal circumference, products of lipid oxidation, pro-inflammatory cytokine expression (IL-1β);- ↑ anti-inflammatory cytokine expression (IL-10)." (PMID 33693024, 2021). "The Con-Can mice in this study showed higher body weight gain and insulin resistance, two important features of metabolic syndrome and risk factors for systemic and chronic inflammation; therefore, we examined the protein expression of NF-κB, STAT3, VCAM, NLRP3, and IL-1β in peritumor tissues." (PMID 34876963, 2021). "Indeed, the plant extract may act as antagonist of TNF-α and IL-1β leading to the reduction of insulin resistance and to antihyperglycemia effects as observed in the study." (PMID 33293987, 2020). "Secretion of adipokines (e.g. leptin) and cytokines (e.g. TNF-α, IL-6 and IL-1β), oxidative stress and, possibly, the gut microbiome contribute to pregnancy-induced insulin resistance, although understanding of pregnancy-induced insulin resistance is incomplete." (PMID 32556615, 2020). "IL-1β activates ІкВ βkinases and thus may induce insulin resistance." (PMID 33072216, 2020). "However, longer exposure to HFD and insulin resistance increases IL-1β mRNA in the hippocampus." (PMID 31992349, 2020). "Therefore, DCs-derived IL-1β might mediate the development of insulin resistance in obese adipose tissue." (PMID 32545355, 2020). "Our study found that administration of a vitamin-rich carbohydrate beverage (5 ml by gavage) could effectively attenuate postoperative insulin resistance, improve insulin sensitivity, and decrease the production of IL-1β and S-100β in the plasma of elderly rats after splenectomy." (PMID 31092210, 2019). "In addition, in patients treated with statins, canakinumab might even be able to reduce statin-induced insulin resistance as this is thought to depend on the activation of the NLRP3 inflammasome/IL-1β pathway." (PMID 31652822, 2019). "Cytokines and chemokines, such as tumor necrosis factor alpha (TNF-α) and interleukin-1 beta (IL-1β), produced by adipose tissue macrophages (ATMs) in an M1 pro-inflammatory state have been identified as crucial effectors in the initiation of inflammation and the development of insulin resistance." (PMID 28515792, 2017). "Consistent with a recent published study, the replacement of saturated fatty acid for monounsaturated fatty acid in high fat diet could ameliorate IL-1β-mediated adipose dysfunction and insulin resistance in mice, highlighting the special role of saturated acid in NLRP3 inflammasome activation." (PMID 28261091, 2017). "Therefore, TNF-α, IL-1β and IL-6 secretion under high fructose consumption may account for insulin resistance, chronic inflammation and endothelial dysfunction in local tissues and organs." (PMID 28353649, 2017). "The control of IL-1β expression might provide a direct link between HIF1α activity in obese ATMs, either activated via hypoxia or inflammatory signalling, and the presence of insulin resistance." (PMID 26940592, 2016). "Since insulin resistance and metabolic dysfunction are closely related to inflammatory status, we checked proinflammatory cytokine levels in plasma, and found plasma levels of IL-1β and IL-6 were reduced by LFE treatment (300 mg/kg) (by 98.2 ± 12.0% and 35.3 ± 8.96%, respectively)." (PMID 27176632, 2016). "Furthermore, IL-1β may constitute a cell-cell mediator in metainflammation, as IL-1β produced by TNFα-stimulated mouse adipocytes has been shown to induce insulin resistance in liver cells." (PMID 24918199, 2014). "We also found that IL-1β blockade can substantially reduce macrophage-stimulated release of the proinflammatory cytokines and lipid mobilization in human adipocytes, which could provide a mechanistic link between IL-1β and insulin resistance at local and also systemic levels." (PMID 24918199, 2014).